TNF (tumor necrosis factor)
Diseases named in the same sentence as TNF in open-access papers (continued):
Sharing a sentence is not in itself a finding about the gene and the disease.
melanoma (continued). "By setting the number of shear-resistantly arrested melanoma cells to 100% for both conditions, the TNF-α-stimulated and the IL-1β-stimulated pMBMECs, we revealed an adhesion-independent increased melanoma cell intercalation into the barrier-compromised IL-1β-stimulated pMBMECs." (PMID 37894438, 2023). "Its growth inhibitory effects are mediated by cell cycle G1-arrest associated with DNA damage and induction of apoptosis while other studies on murine melanoma cells showed that piperine treatment significantly reduced proinflammatory cytokines such as TNF-α, IL-1β and IL-6." (PMID 36768978, 2023). "Similarly, all three melanoma cell lines showed enhanced adhesion to IL-1β-stimulated pMBMECs compared to TNF-α-stimulated pMBMECs, although the data from the YUMM1.1 parental cell line were not significant." (PMID 37894438, 2023). "To analyse the pathway, we employed the flow chamber setup in which only melanoma cells that had shear-resistantly arrested could subsequently intercalate into TNF-α stimulated pMBMECs." (PMID 37894438, 2023). "Alternatively, NK cells might eliminate melanoma cells through the secretion of TNFα and IFNγ promoting Th1 differentiation and the recruitment of CD8+ T cells into regressing tumors." (PMID 37526660, 2023). "UA could significantly inhibit the production of TNF-α, IL-1β, IL-6 and GM-CSF gene expression and production by B16F-10 melanoma cell in culture in a dose-dependent manner." (PMID 36768978, 2023). "Finally, TNF signalling (upregulated in dKO mice) in activated melanoma-infiltrating CD8+ T cells triggers their death." (PMID 37605008, 2023). "Preclinical data have demonstrated that TNF-α blockade promotes the infiltration of activated T cells induced by ICI treatment and that combination therapy with anti–CTLA-4 and anti–PD-1 with TNF-α blockade improves tumor responses and decreases irAEs in mouse models of melanoma and colon cancer." (PMID 37958355, 2023). "In melanoma, TNFα inhibition promotes CD8 infiltration into the tumor." (PMID 36996146, 2023). "Cumulatively, our data suggest that TNFR2 could be utilized as a biomarker to identify melanoma patients that may benefit from TNF-targeting therapies." (PMID 35879777, 2022). "However, we observed a collapse in the proportions of circulating TNF-α-expressing B cells in melanoma patients compared to matched HV evident across all B cell stimulation conditions." (PMID 35909944, 2022). "Furthermore, we pretreated mice with LPS and TNFα for 5 h and injected B16-F10 melanoma cells into the tail vein of WT and cKO." (PMID 35918322, 2022). "While studies have identified TNF as a potent inducer of MAPKi resistance in BRAFV600E+ melanomas, the prevalence of this adaptive resistance mechanism remains unclear." (PMID 35879777, 2022). "Also, MEKi treatment was shown to partially or completely restore the suppressed production of IL-12 and TNF in DCs mediated by melanoma cells and reverse the melanoma-induced downregulation of costimulatory molecules and activation markers of DCs." (PMID 35965494, 2022). "Moreover, CD117- ILCs and CD117+ ILCs from melanoma patients showed impaired TNFα secretion when activated ex vivo with PMA/ionomycin in comparison with ILCs from healthy individuals, consistent with observations in hematological malignancies." (PMID 35173725, 2022). "At functional level, we showed an impaired secretion of TNFα by both CD117- ILCs and CD117+ ILCs from melanoma patients, as reported in blood tumors, and the capability of Nivolumab to enhance the secretion of IL-13 and TNFα by ILC2s and CD117+ ILCs, respectively." (PMID 35173725, 2022). "Studies have shown that TNF-α treatment of melanoma can induce consistent dedifferentiation." (PMID 36124033, 2022).
melanoma (continued). "We found that while WT-PP6 reconstituted PP6−/− MEFs were highly sensitive to TNFα-mediated cell death; PP6−/− MEFs reconstituted with phosphatase-inactive D84N-PP6 or melanoma-associated G112E, H114Y, and G189R mutants remained resistant to TNFα induced cell death." (PMID 36071040, 2022). "The combination of IL-12/IL-18 administration was also tested in grey horses bearing melanoma; meanwhile, increased levels of TNF-α and IFN-γ secreted from peripheral mononuclear blood cells extracorporeally and decreased levels of IL-10 secretion were observed." (PMID 36428682, 2022). "Both TNFα and IL-13 have been suggested to exert a positive role against melanoma cells." (PMID 35173725, 2022). "In the same study, TNF-α blockade overcame resistance to anti-PD-1 therapy in melanoma mice models." (PMID 35743911, 2022). "In addition, micro-environmental cues were shown to induce phenotype switching in melanoma cells in vitro, such as TNFα, TGF-β and hypoxia, all known inducers of EMT in carcinoma models." (PMID 35432344, 2022). "Melanoma cells addition up-regulated TNFα in all the three ILC subsets and IL-13 in ILC2s." (PMID 35173725, 2022). "Tumor necrosis factor (TNF)-α has been identified as a key cytokine impacting melanocytic antigens and leading to the failure of adoptive T-cell transfer therapies (ACTs) in the transgenic mouse-derived HCmel3 melanoma cell line." (PMID 36551603, 2022). "In addition, recent studies suggested that TNF-α and metalloproteases were key players in melanoma cells aggressiveness." (PMID 36132145, 2022). "Moreover, the ratio of TGF-β+:TNF-α+ B cells was significantly increased in melanoma patients compared to matched HV, suggesting an overall skew toward regulatory cytokine expression in patient B cells." (PMID 35909944, 2022). "Therefore, the discovery for the role of PP6 in modulating TNFα-mediated cell death provides new insights into the mechanism that promotes melanoma progression." (PMID 36071040, 2022). "In the present study, we investigated the prevalence of TNFR2 expression by human BRAFV600E+ melanomas and whether it plays a role in TNF-mediated resistance reprogramming to MAPKi." (PMID 35879777, 2022). "Interestingly, the treatment of human melanoma cells with TNFα alone recapitulated the phenotype switch observed in their in vivo model." (PMID 35432344, 2022). "Recent reports show a “bidirectional communication” between melanoma cells and adipocytes, especially in obese patients, consisting of the secretion of high amounts of pro-inflammatory factors such as IL-6, IL-11, TNF-α, monocyte chemoattractant protein (MCP)-1/CCL2, and PAI-1 by the excessive fat." (PMID 35334544, 2022). "We report that only a subset of melanomas acquire MAPKi resistance in response to TNF exposure." (PMID 35879777, 2022). "Moreover, melanoma cells boosted TNFα production in all ILC subsets and increased the number of IL-13 producing ILC2s in vitro." (PMID 35173725, 2022). "Partial effectiveness of TNF inhibitors to neutralize macrophage-induced resistance to MAPKi by BRAFV600E+ melanoma could be attributed to the ability of macrophages to release solTNF and VEGF, two factors central to their MEKi-promoting functions." (PMID 35879777, 2022). "Indeed, TNFα induced dedifferentiation of melanoma cells and abrogated immune recognition by adoptively transferred pmel-1." (PMID 35406721, 2022). "Indeed, TNFα is successfully used to treat in transit melanoma metastases and its presence within tumors has been shown to be induced by and synergize with ICIs in melanoma patients, while its systemic blockage is associated with a reduced survival." (PMID 35173725, 2022). "Melanoma-specific survival (MSS) was also shorter in patients who received TNF inhibition." (PMID 35538491, 2022). "The pro-inflammatory TNFα can promote an interconversion among melanoma phenotypes." (PMID 35406721, 2022).
melanoma (continued). "In addition, researchers proved that TNF-α delivery can enhance the antitumor activity of antibody-dependent cell–mediated cytotoxicity of an anti-Melanoma Immunoglobulin, peptide anticancer vaccine, and cancer cell membrane targeting therapy." (PMID 36110523, 2022). "More importantly, we identify TNFR2 as a key component to this mechanism and provide evidence that it can potentially be used as a biomarker of melanomas that might benefit from combination MAPKi and TNF-targeting therapies." (PMID 35879777, 2022). "Besides, other immunomodulatory molecules, TLR, TNFα and IL-10 are also appealing for potential combination with ICBs to treat melanoma." (PMID 34924562, 2021). "Indeed, although high levels of TNFα inhibit tumor growth, secretion of low levels of TNFα by cancer cells in a B16 mouse melanoma model furthers the recruitment of infiltrating myeloid cells, promoting cancer vascularization and progression." (PMID 34360868, 2021). "Moreover, T-cell derived TNF-α has been demonstrated to kill tumor cells and loss of TNF-α increases melanoma tumor cell invasion in the lung." (PMID 34531874, 2021). "In addition to the Kyn-dependent pathway, AhR activation by FICZ (6-formylindolo [3,2-b]carbazole), a skin tryptophan photoproduct, was shown to promote TNFα-dependent inflammation and induce melanoma cell differentiation and the development of metastasis." (PMID 33451095, 2021). "On the other hand, TNF may be involved in the immune escape of melanoma by the reduction of tumor-infiltrating CD8+ T cells, which is mediated by TNFR1." (PMID 34068679, 2021). "One of our major findings is that the overexpression of TNFα in engineered colorectal carcinoma and melanoma cell lines is not linked with significant affection of the subpopulation of CSCs in vitro." (PMID 33957885, 2021). "Introducing the protein into human melanoma cells was shown to inhibit TNF, IL-1, TLRs, and TNF receptor-associated factor 2- (TRAF2-) induced NF-κB activation, thereby restoring the SAPK or NF-κB response to TNF activation." (PMID 34194957, 2021). "Additionally, inhibition of PD-1 significantly enhances human and mouse ILC2 TNF-α production, a cytokine with the potential to directly induce apoptosis in B16 melanoma cancer cells." (PMID 34531874, 2021). "The transduction of melanoma cells with plasmids encoding BRAFV600E-specific short hairpin RNA significantly reduced the inhibitory properties of melanoma cell culture supernatants on the production of pro-inflammatory cytokines such as IL-12 and TNF-α by lipopolysaccharide (LPS)-stimulated DC." (PMID 34576054, 2021). "Further, the melanoma cell state-specific changes did not reflect differences in TNFα signaling, as determined by the loss of the IκB protein." (PMID 34073253, 2021). "In this study, we examined the pleiotropic effects of TNFα on 40 melanoma cell lines." (PMID 34073253, 2021). "However, the senescence was not induced in colorectal carcinoma cells HT29hTNFa and HCT116hTNFa suggesting the two different mechanisms of TNFα action in carcinoma cells and in melanoma cells." (PMID 33957885, 2021). "Studies have shown that administration of TNF-α as an immunotherapy has resulted in high levels of toxicity, but localized delivery in isolated limb perfusion showed anti-tumor abilities in soft tissue sarcomas, melanoma, and hepatocellular carcinoma." (PMID 34012451, 2021). "We found that although TNFα signaling was intact in all melanoma cells, the response to TNFα was dependent on the differentiation status of melanoma cells, with the melanocytic and transitory melanomas showing more pronounced downregulation of the pigmentation regulator MITF." (PMID 34073253, 2021). "Recently, in a phase Ib study, it was found that the TNF blockers (infliximab or certolizumab) helped to mitigate the immune-related adverse events in melanoma patients undergoing treatment with immune checkpoint inhibitors (ICIs) while enhancing their antitumor effect." (PMID 33801589, 2021).
melanoma (continued). "Importantly, they also showed that TNFα blockade enhanced the antitumor effect of immune checkpoint inhibitor treatment in melanoma and colon cancer, revealing that TNFα mediates irAEs." (PMID 33540543, 2021). "The cell surface expression of PD-L1 was also low in our panel of melanoma cells at baseline and after TNFα induction, although the PD-L1 transcript and protein are both significantly induced, and we have previously shown that this molecule is also highly inducible by IFNγ." (PMID 34073253, 2021). "One critical effect of TNFα is the induction of melanoma dedifferentiation, characterized by the downregulation of the melanocytic antigen Melan A (MLANA gene) and the microphthalmia-associated transcription factor MITF, and the upregulation of NGFR and the AXL receptor tyrosine kinase." (PMID 34073253, 2021). "It is known, that TNFα triggers premature senescence in various cell types, such as endothelial, epithelial, and leukemic cells and here we can confirm the senescence induction also in malignant melanoma cells." (PMID 33957885, 2021). "Furthermore, in the B16 melanoma model, the percentage of TNF-α-producing ILC2s significantly increases, suggesting the melanoma tumor microenvironment is primed to allow for ILC2 TNF-α secretion." (PMID 34531874, 2021). "Additionally, in a more aggressive melanoma cell line, higher levels of IL-6, eotaxin, and TNF-α were detected." (PMID 34068679, 2021). "Our results suggest that TNFα promotes dynamic changes in melanoma cells that may favor immunotherapy resistance." (PMID 34073253, 2021). "For example, TAMs upregulate urokinase-type plasminogen activator (uPAR) and secrete MMPs, such as MMP-9, which enable the remodelling of the ECM and increase the invasiveness of melanoma, or they upregulate such factors in melanoma cells through the secretion of TNFα and IL-1α." (PMID 34830780, 2021). "Importantly, treatment of melanoma cellswith TNF suppresses CSCs differentiation through PI3K/AKT signaling." (PMID 34308569, 2021). "Interestingly, MITF was negatively correlated with AXL post TNFα in the dedifferentiated melanoma subtype." (PMID 34073253, 2021). "Alpha-MSH protects melanocytes and melanoma cells from the proinflammatory actions of TNF-α." (PMID 34068618, 2021). "Based on our combined results of PD-1 deficient/inhibitory mouse models and cytotoxicity assay, we propose a novel, direct role of ILC2-derived TNF-α in the apoptosis of B16 melanoma cells that is enhanced by anti-PD-1 therapy in the significant delay of melanoma tumor growth." (PMID 34531874, 2021). "Our results suggest that TNFα produces a dynamic program of transcriptome and protein changes that may favor immunotherapy resistance in melanoma." (PMID 34073253, 2021). "However, hypermethylated melanoma cell lines fail to upregulate CD73 following exposure to HGF/TNFα but do so only when pretreated prior to exposure with the demethylating agent 5-azacytidine." (PMID 33430239, 2021). "TNF-α was reported to directly increase the stem cell-like properties of cancer cells, specifically in the kidney, breast, and colon cancers and melanoma." (PMID 34638319, 2021). "In our study, the B16-F10 murine melanoma cell line is not susceptible to Smac mimetics induced cell death even upon the combination of Smac mimetics and exogenous TNF." (PMID 33546280, 2021). "Additionally, ADAM17 was significantly overexpressed in advanced stage of melanoma, and the expression of TNF-α was up-regulated and significantly correlated with the expression of ADAM17 and respectively, with the advanced tumor stage." (PMID 34224305, 2021). "We initially examined TNFα signaling in response to exogenous TNFα in 40 melanoma cell lines, including 31 cutaneous (11 BRAF-mutant, 10 NRAS-mutant, 10 BRAF/RAS WT) and nine uveal melanoma cell lines (five GNAQ-mutant, three GNA11-mutant and one GNAQ/GNA11 WT)." (PMID 34073253, 2021).
melanoma (continued). "Relative to the control (100%), vitamin D at 0.0002, 0.002, 0.02, and 0.2 μM significantly inhibited IL-1 protein levels to 63%, 62%, 41%, and 44% of control (p < 0.05); and significantly inhibited TNF-α protein levels to 75%, 75%, 80%, and 79% of control (p < 0.05), in melanoma cells." (PMID 32150881, 2020). "In addition, the significant increase of infiltrating immune cells was observed in both tumor models but more so in melanoma, where the expression of IL-12 and TNF-α was determined as well." (PMID 32204304, 2020). "RANKL does not drive tolerance to MAPK inhibition through pathway re‐activation as has commonly been observed, but rather via an increase in MITF expression similar to the TNF‐α mediated increase in MITF that occurs when macrophages are co‐cultured with melanoma cells." (PMID 31323160, 2020). "As H3K27me3 expression has been suggested to be induced by inflammatory stimuli in the microenvironment, we investigated the impact of tumor necrosis factor alpha (TNFα) and interferon gamma (INFγ) stimulation on H3K27me3 expression in a panel of human melanoma cell lines." (PMID 32041674, 2020). "Vitamin D significantly inhibited the expression of IL-1 and TNF-α in melanoma cells." (PMID 32150881, 2020). "In addition, it has been observed that the methylation status and the level of TNF-α expression were inversely correlated in canine melanoma cell lines and melanoma tissues." (PMID 33194754, 2020). "In melanoma-bearing mice receiving IL-2- and TNF-α-coding adenovirus in combination with adoptive T-cell therapy, PD-L1 was upregulated in intratumoral MDSCs, and the frequency of PD-1+ CD8+ T cells correlated with the PD-L1 expression level on MDSCs in tumor site." (PMID 32793192, 2020). "Hypermethylation of TNF-α has been shown in human and canine melanoma cells by performing MSP." (PMID 33194754, 2020). "An exception is the use of local TNF administered locally by isolated limb perfusion treatments in melanoma and sarcoma, or in isolated hepatic perfusion for treatment of liver metastasis which have demonstrated that TNF alone or in combination to cause large response rates of up to 80%." (PMID 32805626, 2020). "Another evidence of the ability of TNFα to impair the function of antitumor immune cells is that, in melanoma, the cytotoxic response against the tumor that is carried out by CD8+ T lymphocyte is inhibited by this cytokine, which is produced by CD4+ lymphocytes infiltrating the tumor." (PMID 32391269, 2020). "Microglia-derived IL-1α and TNF-α were found to upregulate GM-CSF secretion from melanoma cells." (PMID 32668704, 2020). "In addition, birinapant, an SM, in combination with TNFα, was reported to inhibit the growth of melanoma, including the serine/threonine-protein kinase B-raf (BRAF) inhibitor-resistant cell line." (PMID 32325691, 2020). "Indeed, there is a strong rationale in the melanoma mouse model showing that TNF signaling impairs accumulation of CD8+ TILs." (PMID 33142728, 2020). "Similarly, our work also indicated that Abx combined with the anti‐tumor drug DSF/Cu2+ had significantly inhibited the tumor growth in the melanoma‐bearing mice, accompanied by the reducing of inflammatory cytokines IL‐1β, IL‐6, and TNF‐α." (PMID 32750218, 2020). "Secretion of soluble factors such as VEGF-A, TNFα, and TGFβ from melanoma and lung cancer models has been previously demonstrated to induce the expression of inflammatory chemoattractants such as S100A8 and S100A9 in the premetastatic lungs, leading to myeloid cell recruitment." (PMID 33233625, 2020). "In addition, in an adoptive CD8+ T cell transfer protocol, TNFα induced the dedifferentiation of melanoma cells, facilitating immune escape and melanoma relapse." (PMID 32391269, 2020).